TNF (tumor necrosis factor)
Diseases named in the same sentence as TNF in open-access papers (continued):
Sharing a sentence is not in itself a finding about the gene and the disease.
periodontal disease (continued). "Therefore, the objective of this work was to analyze the cytokines IL-2, IL-6, IL-10, and TNF-α and inflammatory mediators such as PGE2 in pregnant patients at risk of preterm delivery and their relationships with periodontal disease." (PMID 30154640, 2018). "Porphyromonas gingivalis, a Gram-negative anaerobic bacillus, is one of the pathogens involved in the progress of periodontal disease, and inflammatory cytokines such as interleukin and tumor necrosis factor in periodontal disease promote periodontal tissue destruction." (PMID 29659496, 2018). "Thus, TNF-α appears to be a key mediator in the pathogenesis of periodontal disease, T2DM, and diabetic renal disease." (PMID 28431542, 2017). "The elevated concentrations of serum IL-1β, β-glucuronidase, and TNF-α-accompanying saliva mediators suggested periodontal disease might be one of the factors triggering a systemic inflammatory response." (PMID 29017560, 2017). "This study aimed to evaluate the effects of β-glucan ingestion (Saccharomyces cerevisiae) on the plasmatic levels of tumor necrosis factor-α (TNF-α) and interleukin-10 (IL-10), alveolar bone loss, and pancreatic β-cell function (HOMA-BF) in diabetic rats with periodontal disease (PD)." (PMID 28906456, 2017). "The result of study by Geng and Rai showed that TNF-α can be a biomarker for periodontal disease." (PMID 29238418, 2017). "This reduction of the level of salivary TNF-α could be a reflection of reduced RA disease activity and also might affect the inflammatory components of periodontal disease." (PMID 28061876, 2017). "Scaling and root planning improved periodontal disease indices and salivary TNF-α and IL-1α levels." (PMID 29238418, 2017). "The elevated concentrations of serum IL-1β, β-glucuronidase, TNF-α accompanying with the saliva mediators suggested periodontal disease might be one of the factors triggering a systemic inflammatory response." (PMID 27978823, 2016). "Studies confirm that certain salivary biomarkers, i.e. IFN-γ, IL-1-β1, TNF-α, IL-6, IL-4 and IL-8, may be used for predicting future development of periodontal diseases." (PMID 25976216, 2015). "Moreover, it was confirmed that the severity of the periodontal disease and the serum levels TNF-α, IL-6 and CRP were significantly correlated." (PMID 26644840, 2015). "Our results from the baseline visit of the QUALITY cohort so far indicate that obese boys, but not girls, have 37% higher levels of TNF-α, a risk factor for destructive periodontal disease, in their gingival crevicular fluid (GCF) compared to nonobese boys." (PMID 24068858, 2013). "Furthermore, anti-RANKL and anti-TNFα antibodies significantly inhibited osteoclastogenesis suggesting that T cells support spontaneous osteoclastogenesis in periodontal disease via RANKL and TNFα overexpression." (PMID 24278766, 2013). "In periodontal diseases, inflammatory mediators, including interleukin (IL)-6, IL-8 and tumor necrosis factor-α (TNF-α), may promote the degeneration of inflamed periodontal tissues." (PMID 24137277, 2013). "In addition, our team previously reported that the therapy of periodontal disease leads to the reduction in TNF-α in Japanese subjects." (PMID 22117840, 2011). "Experimental periodontal disease rats showed an intense bone loss compared to SO ones (SO = 1.61 ± 1.36; EPD = 4.47 ± 1.98 mm, p < 0.001) and evidenced increased cellular infiltration and immunoreactivity for TNF-α and iNOS." (PMID 20546603, 2010). "Periodontal disease being a chronic infection, shares pathogenic mechanisms of cardiovascular diseases with the release of some inflammatory mediators like PGE2, IL-1, IL-6, and TNF-α." (PMID 20407653, 2009). "In particular, a sample’s positivity to CMV should be investigated if the positive result is for the latent or active form of CMV, which may have a direct role in inflammatory cytokines (like interleukin-1β and TNF-α) and periodontal disease progression, promoting osteoclastogenesis." (PMID 40871317, 2025).
periodontal disease (continued). "Therefore, treating periodontal disease not only reduces pro-inflammatory mediators such as IL-6, tumor necrosis factor-α (TNF-α), CRP, and reactive oxygen species (ROS), but also increases the levels of pro-resolving lipid mediators, which are crucial for maintaining homeostasis." (PMID 40916006, 2025). "In addition to the biomarkers assessed, the inclusion of other parameters such as MMP-8, IL-1β, and TNF-α could provide comprehensive insights into the pathogenesis of periodontal disease." (PMID 41300847, 2025). "Additionally, inflammatory cytokines, such as MMP-9, TNF-a, and IL-6, which are increased in periodontal disease, could potentially impact lung health through aspiration." (PMID 38909262, 2024). "Additionally, TNF-α present in the GCF could be used for the diagnosis of periodontal diseases/inflammation, as its increased concentration in GCF was remarked in patients suffering from periodontal diseases at different stages." (PMID 36902030, 2023). "Interaction between anti‐ Eno antibodies and Eno‐positive cells that express in synovial fluid and peripheral blood mononuclear cells may contribute to the elevated TNFα serum levels in patients with RA, and the circulating TNFα may contribute to the progression of periodontal disease." (PMID 37225674, 2023). "Also, they showed that IL-1β and TNF-α are promising biomarkers in detecting periodontal disease." (PMID 37224312, 2023). "The study also confirmed a log-linear relationship between TNF-α levels and red complex bacteria, thereby demonstrating the role of inflammatory biomarkers in periodontal disease progression that could contribute to the development of systemic inflammation such as CKD." (PMID 35336824, 2022). "Therefore, it has been suggested that TNFα in GCF could serve as a potential biomarker for the diagnosis of periodontal diseases." (PMID 33513808, 2021). "The decreased monocyte chemotaxis and phagocytosis, the increased production of TNF-alpha, IL-4, IL-10 and IL-1, as well as the increased susceptibility to infections and the delayed healing response, explain the susceptibility of HIV-positive individuals to periodontal disease." (PMID 33916511, 2021). "In patients with periodontal disease, the degree and frequency of endotoxemia is increased with the severity of the disease, which contributes to systemic inflammation, including increased blood levels of C‐reactive protein, IL‐6, and tumor necrosis factor alpha." (PMID 34463983, 2021). "We could not confirm a significant association of IL-1α and TNF-α with periodontal disease in the present study." (PMID 34199256, 2021). "However, elevated levels of TNF-α, IL10, IL-6, IL-1β and IL-8 were observed in the CP group, which may increase the susceptibility and progression of periodontal disease in these individuals." (PMID 32509226, 2020). "Studies concerning oral diseases, such as periodontal diseases, lichen planus or oral carcinoma, demonstrated the increased salivary levels of selected pro-inflammatory nuclear factor-κB dependent cytokines, e.g., interleukin 1β (IL-1β), interleukin 6 (IL-6), tumour necrosis factor α (TNF-α)." (PMID 33050496, 2020). "Increased salivary TNF-α due to inflammation may generate periodontal diseases." (PMID 33202617, 2020). "Adipose tissue-derived inflammatory response such as increased tumor necrosis factor-α (TNF-α) production is suggested to exacerbate the systemic low-grade inflammation, which further act as a deteriorating factor for other inflammatory diseases such as periodontal disease and inflammation." (PMID 32346618, 2020). "Together with the pathological mechanism proposed in Section 2.1 of this review article (IR involvement), the study of TNF-alpha and other proinflammatory cytokines could provide a thorough explanation for the possible chronic hepatitis C infection and periodontal disease connection." (PMID 29725605, 2018).
periodontal disease (continued). "Kim and collaborators showed a reduction in TNF-α levels in rats with ligature-induced periodontal disease treated with β-glucan (Polycan) daily, suggesting that the progression of periodontal disease may be delayed by antagonists to specific mediators of the host." (PMID 28906456, 2017). "Furthermore, the model presented may elucidate important CHD biomarkers which should be measured in patients with periodontal disease to more adequately screen for CHD risk, namely HOMA, TNF-α, CRP, IL-6, GDF-15, OPG, MPO and fibrinogen." (PMID 27846870, 2016). "Therefore elevation of CRP & TNF-α such as that seen in periodontal disease may supplement systemic vascular inflammation, atheroma formation and add to the pre existing risk for cardiovascular sequelae." (PMID 24198887, 2013). "High levels of interleukin-1 (IL-1), interleukin-6 (IL-6), prostaglandin E2 (PGE2), and TNF-α have been detected in the gingiva and gingival crevicular fluid (GCF) of patients with periodontal disease." (PMID 40323540, 2026). "Toll-like receptors (TLR-2 and TLR-4) and tumor necrosis factor-alpha (TNF-α) are key mediators of immune signaling and tissue breakdown, making them potential biomarkers of periodontal disease activity." (PMID 42154854, 2026). "High amounts of TNF- α, IL-1, IL-6, and PGE2 have been detected in the GCF of patients with periodontal disease, indicating that local inflammatory cytokines also play an active role in periodontal disease-related pathologies." (PMID 40323540, 2026). "Analogous to periodontal disease, the pathogenesis of IBD involves aberrant immune system activation, with pro-inflammatory mediators, including TNF-α, IL-1β, and IL-6, orchestrating the immune microenvironment and driving disease progression." (PMID 40002889, 2025). "Cytokines such as IL-1β, TNF-α, IL-6, and RANKL are pivotal in managing the immune response in periodontal diseases." (PMID 38595889, 2024). "Inflammatory Markers: Periodontal disease can lead to elevated levels of systemic inflammatory markers such as C-reactive protein (CRP), tumor necrosis factor-alpha (TNF-α), and various interleukins (IL-1, IL-6, IL-8)." (PMID 39610974, 2024). "Periodontal disease (PD) contributes to systemic inflammation by releasing mediators such as C-reactive protein (CRP), interleukins (IL-1, IL-6), tumor necrosis factor (TNF)-α, and α-1-antichymotrypsin into the body's circulation." (PMID 39044527, 2024). "Numerous studies have shown differences in TNF-α levels in saliva, serum, tissue biopsies, PICF and GCF of subjects with periodontal disease." (PMID 38431633, 2024). "The authors investigated the role of MMP-8, 9, IL-1β, IL-6, and TNF-α along with MIP-1α and found that MIP-1α had the highest discriminatory role in periodontal disease among adults." (PMID 38433948, 2024). "Many inflammatory mediators, including the inflammatory cytokines interleukin-1 beta (IL-1β), tumor necrosis factor-alpha (TNF- α), and prostaglandin E2 (PGE2) have been found in saliva during the development and progression of periodontal disease." (PMID 36747174, 2023). "Numerous pieces of research have shown that inflammatory cytokines like tumor necrosis factor alpha (TNF-α), C-reactive protein (CRP), and interleukin-6 play a role in the connection between PCOS and periodontal disorders." (PMID 38021744, 2023). "We previously reported that the severity of periodontal disease may be associated with the expression of the ADAM17 gene in the human buccal mucosal epithelium, and that ADAM17 is strongly expressed in the epithelium of gingival tissues and regulates the production of TNF-α from oral keratinocytes." (PMID 35200250, 2022). "Similar inflammatory mediators, such as IL-6, TNF- α, and CRP, are increased in patients with severe periodontal disease (PD)." (PMID 36361416, 2022). "Pro-inflammatory cytokines, IL-1β, IL-6, TNF-α, and IFN-γ, have a major role in the pathogenesis of periodontal disease and were also detected in healthy GCF samples." (PMID 35048035, 2021).
periodontal disease (continued). "Patients with severe symptoms of COVID-19 have increased IL-1, IL-7, IL-10, IL-17, IL-8, TNF and MCP-1 serum levels when also afflicted with periodontal disease." (PMID 34437404, 2021). "For example, several cytokines and chemokines known to be involved in the etiology of periodontal disease were also detected in clinically healthy GCF, such as TNF-α and IL-1β." (PMID 35048035, 2021). "In an experimental periodontal disease model, gliclazide treatment reduced myeloperoxidase activity, MDA, IL-1β and TNF-α levels via downregulation of PI3K and AKT (Araújo and Morais, 2019)." (PMID 34227646, 2021). "In this study, it was observed that in situ the expression of TNF-α was significantly decreased and the expression of IL-10 was significantly increased in BAFF blockade mice with periodontal disease." (PMID 34481478, 2021). "Inflammatory cytokine biomarkers, such as interleukin-1 beta (IL-1β), interleukin-6 (IL-6), and tumor necrosis factor alpha (TNF-α) are significantly elevated in patients with cardiovascular and periodontal disease." (PMID 34299815, 2021). "The biomarkers showing elevated levels in the baseline saliva of patients with periodontal disease were IL-1β, IL-4, IL-6, MMP-8, and TIMP-2, while the control group showed high levels of TNF-a, IL-10, IL-17, and IL-32." (PMID 33383828, 2020). "In the course of periodontal disease, various proinflammatory mediators occur, such as interleukin- (IL-) 1, IL-6, and IL-8, IFN- γ, CCL5, TNF-α, prostaglandins, and metalloproteinases." (PMID 31355282, 2019). "Patients with periodontal disease had significantly higher serum CRP, IL-6 and TNF-α values by comparison with healthy subjects." (PMID 26644840, 2015). "To summarize, the diabetic patients with periodontal disease had significantly higher serum CRP, IL-6 and TNF-α values by comparison with healthy subjects." (PMID 26644840, 2015). "Before melatonin treatment, serum TNF-α, IL-6 and CRP levels in diabetic patients with periodontal disease were significantly higher than in healthy control subjects." (PMID 26644840, 2015). "This prospective, non-randomized interventional study evaluated TLR-2, TLR-4, and TNF-α levels in gingival crevicular fluid (GCF) for periodontal disease monitoring and assessed the effects of nonsurgical periodontal therapy (NSPT) on clinical parameters." (PMID 42154854, 2026). "In contrast to the investigations of VEGF-A, the results concerning TNF-α in the pathophysiology of periodontal diseases were not contradictory." (PMID 40426985, 2025). "Periodontal diseases contribute to systemic health issues by triggering chronic inflammation, as evidenced by elevated levels of biomarkers like C-reactive protein (CRP), interleukin-6 (IL-6), and tumor necrosis factor-alpha (TNF-α)." (PMID 40418274, 2025). "Potential biological pathways through which periodontal diseases can negatively affect human milk composition include the systemic dissemination of inflammatory cytokines like IL-6, PGE2, and tumor necrosis factor (TNF)-β that can be up-regulated by bacterial by-products." (PMID 39540631, 2024). "Correspondingly, previous Iraqi studies demonstrated a statistically significantly positive correlation of TNF-α levels with periodontal destruction parameters (PI, GI, PPD, and CAL), demonstrating this cytokine’s contribution to the onset of periodontal disease." (PMID 36794778, 2023). "Once periodontal disease is established, lipopolysaccharides and inflammatory cytokines, particularly Interleukin (IL)-1β, Prostaglandin E2 (PGE2) and Tumor Necrosis Factor (TNF)-α enhance a biologic burden which initiates the onset and progression of atherogenesis and thromboembolic events." (PMID 38077410, 2023).
periodontal disease (continued). "The translocation of periodontal pathogens to the fetoplacental unit or the effect of inflammatory mediators, like interleukin-1 (IL-1), IL-6, IL-8, tumor necrosis factor-α (TNF-α), or prostaglandin E2 (PGE2), explains the possible link of periodontal diseases and various adverse pregnancy outcomes." (PMID 35706459, 2022). "TNFα (p = 0.0038), MCP1 (CCL2) (p = 0.0493), IL-1β (P = 0.0043), and IL-8 (p = 0.0035) were increased in OSCC compared to control only while MIP1β (CCL4) (p < 0.0365) was increased in OSCC patients compared to periodontal disease patients." (PMID 35048057, 2021). "Biomarkers showing high levels in periodontal disease were salivary IL-1β, IL-4, IL-6, MMP-8, and tissue inhibitor of matrix metalloproteinases (TIMP)-2, and those in the controls were tumor necrosis factor (TNF)-α, IL-10, IL-17, and IL-32." (PMID 33383828, 2020). "According to a recent systematic review, TNF-α seems to be a reliable biomarker for diagnosis of periodontal disease but not to monitor the periodontal healing." (PMID 33218047, 2020). "When RA patients on anti-TNF therapy (mean of 26 months) were compared to a control group, patients with periodontal disease, without RA or another systematic inflammatory disease and no anti-TNF therapy, BOP and CAL showed also significantly lower parameters." (PMID 33193432, 2020). "Nevertheless, there is no general agreement on the relationship between periodontal disease and gingival crevicular fluid levels of TNF-α and IL-8 in patients with normal renal function." (PMID 31382656, 2019). "According to our results, IL-6 and TNF-α salivary levels appears to have potential to distinguish pregnant women with and without periodontal disease." (PMID 29740515, 2018). "Treatment with β-glucans reduced the TNF-α blood levels in diabetic animals with periodontal disease and IL-10 levels in diabetic and nondiabetic animals with periodontal disease (p < 0.05)." (PMID 28906456, 2017). "Inflammatory mediators includinginterleukin-1 beta (IL-1β), IL-6, tumor necrosis factor alpha (TNF-α) and beta-glucuronidase (β–glucuronidase) were tested and analyzed among women with overall periodontal disease (n = 442) or moderate/severe periodontal disease (n = 247)." (PMID 27978823, 2016). "Serum IL-1β and TNF-α levels were significantly higher in women with overall periodontal disease compared with women without periodontal disease." (PMID 27978823, 2016). "In addition, periodontal disease patients with CKD indicators had a higher percentage of high of CRP (≥1.03 mg/L), high TNF-α (≥1.12 ng/L) and high IL-6 (≥7.54 ng/L) levels than those without indictors of kidney damage." (PMID 23951003, 2013). "TNF-α induces bone resorption and upregulates PGE2 and MMP secretion during periodontal disease." (PMID 22315682, 2012). "While no prior studies have specifically investigated CTRP-1 in periodontal disease, its role as a modulator of inflammation- through its influence on pro-inflammatory molecules such as TNF-α and IL-6- has been well established in other inflammatory conditions." (PMID 40542868, 2025). "Numerous studies show that patients with periodontal disease have elevated levels of systemic inflammatory mediators compared to healthy controls, including C-reactive protein (CRP), interleukin 1 (IL-1), interleukin 6 (IL-6), and tumor necrosis factor-α (TNF-α)." (PMID 40026941, 2025). "Further clinical trials could focus on immunological markers like aMMP-8, sIL-6R, calprotectin, IL-6, TNF-α, IL-1 in people without advanced periodontal disease and periodontally severe diseased people to finally clarify the evidence." (PMID 39786483, 2025). "This correlation may be attributed to inflammatory and immunological responses common to both periodontal disease and systemic diseases, leading to an increase in circulating inflammatory cytokines, such as C-reactive protein (CRP), interleukin (IL)-6, and tumor necrosis factor (TNF)-α." (PMID 38132221, 2023).